OR8D2 (olfactory receptor family 8 subfamily D member 2)
Description:
Odorant receptor (Potential). May be involved in taste perception.
Synonyms: JCG2
Tractability: Antibody: UniProt places it where antibodies can reach, with medium confidence; UniProt predicts a signal peptide or a membrane-spanning region; its Gene Ontology location is reachable by antibodies, with medium confidence.
Gene: Protein-coding gene on chromosome 11 (124,319,262 to 124,320,197, reverse strand). Ensembl gene ENSG00000279116.
Subcellular location: Cell membrane
Pathways (Reactome):
Sensory Perception: Expression and translocation of olfactory receptors
Gene Ontology:
Molecular function: olfactory receptor activity; G protein-coupled receptor activity
Biological process: G protein-coupled receptor signaling pathway; sensory perception of smell; detection of chemical stimulus involved in sensory perception of smell
Cellular component: plasma membrane; membrane
Genetic constraint (gnomAD): Missense variants: 342 observed, 373.16 expected, observed/expected ratio (o/e) 0.92, 90% interval 0.84 to 1. Synonymous variants: 152 observed, 142.9 expected, observed/expected ratio (o/e) 1.06, 90% interval 0.93 to 1.22.
Homologues: Orthologues: chimpanzee OR8D2 (97% identical), mouse Or8d2 (84% identical), rabbit OR8D2 (84% identical), pig OR8D2 (83% identical), mouse Or8d2b (81% identical), dog OR8D2 (79% identical), guinea pig OR8D2 (71% identical), tropical clawed frog or5dd2b (46% identical). Paralogues in human: OR8D1 (69% identical), OR8A1 (64% identical), OR8G1 (62% identical), OR8G3 (62% identical), OR8G5 (60% identical), OR8D4 (59% identical), OR8B3 (59% identical), OR8G2P (59% identical), OR8B2 (59% identical), OR8B8 (58% identical), OR8B12 (56% identical), OR8B4 (56% identical), and 84 more.
Diseases named in the same sentence as OR8D2 in open-access papers:
OR8D2 is named in the same sentence as 1 disease in open-access papers, as found by Europe PMC text mining. Sharing a sentence is not in itself a finding about the gene and the disease.
myocardial infarction (1 paper, 2022). Gross necrosis of the myocardium, as a result of interruption of the blood supply to the area, as in coronary thrombosis.